IGF1 (insulin like growth factor 1)
Diseases named in the same sentence as IGF1 in open-access papers (continued):
Sharing a sentence is not in itself a finding about the gene and the disease.
tumor (continued). "Interestingly, serum IGF1 was strongly correlated positively with male gender (r = 0.714, P = 0.01) and negatively with LN metastasis and tumor stage (r = − 0.77, P = 0.006 for each) among the non-obese CRC patients." (PMID 38704452, 2024). "In addition, the IGF1/IGF1R pathway appears to be a key player in enhancing the immunosuppressive function of T-regs and impairing the recruitment of cytotoxic CD8+ T cells at the tumor site." (PMID 38420122, 2024). "In the population evaluated, despite a high rate of tumor size reduction, biochemical control was low, similar to data in the literature where it has been observed that patients with biochemical relapse, especially IGF-1 levels, had normal sella turcica MRI without tumor imaging relapse." (PMID 39803157, 2024). "Furthermore, we discovered that insulin or IGF-1 binds to specific receptors on tumor cell membranes to regulate tumor growth and glucose metabolism by activating the PI3K/AKT/mTOR pathway in EC, meanwhile metformin can reduce plasma IGF-1 concentration thereby exerting anticancer activity." (PMID 38577616, 2024). "Therefore, we hypothesized that regulating IGF1, CDKN2A, BIRC5, and SPP1 levels may affect the tumor immune microenvironment in HCC." (PMID 39042294, 2024). "Collectively, these results suggested that, at least in the tumor microenvironment, IGF1 bioavailability was not compromised by protein restricted diet and could still activate IGF1R overexpressing Mir15aKO PDAC." (PMID 38342897, 2024). "Also, IGFBP-3, one of IGF-1 binding proteins, is thought to have tumor suppressive effects independent of IGF-1, by promoting apoptosis, and inhibiting growth, invasion, and angiogenesis." (PMID 38082056, 2024). "Tumour reduction was not correlated with IGF1 decrease during pasireotide treatment." (PMID 37530039, 2023). "Although tumor-associated myeloid cells promote T-ALL progression by activating IGF1R signaling, which is required for initiation and growth of T-ALL44, exogenous IGF1 alone is not sufficient to support T-ALL survival." (PMID 37805579, 2023). "Meanwhile, IGF1 and IGF1R can induce cell proliferation, promote the transcription and expression of vascular endothelial growth factor genes, promote angiogenesis, provide more nutrients for tumor growth, and promote the further development of CRC to advanced stages." (PMID 37266156, 2023). "Thus, it could reduce cell melanin production and promote cell growth but by also reducing IGF-1 and VEGF mRNA expression, may reduce wound scarring and prevent tumor proliferation and swelling." (PMID 36627306, 2023). "Patients consuming the KD with chemotherapy were found to have reduced tumor sizes by an additional 21mm, lower cancer staging, increased anti-tumorigenic factors of IL-10, reduced factors that promote angiogenesis such as TNF-alpha, insulin, and IGF-1, and a higher survival rate." (PMID 37937022, 2023). "The effects of integrin blockade on tumor growth did not depend on IGF-1- or FBS-concentration." (PMID 35053528, 2022). "Not only could a complete remission of growth hormone (GH) and insulin-like growth factor-1 (IGF-1) not be obtained, but the tumor continued to grow and eventually recurred around the brainstem despite multidisciplinary treatments." (PMID 35712496, 2022). "Besides members of the EGFR family, HER2 dimerize with other membrane-bound receptors, such as insulin-like growth factor 1 (IGF-1), leading to an increase in the phosphorylation of HER2 and consequent activation of tumor-promoting downstream signaling pathways." (PMID 36360302, 2022). "Moreover, IGF-1 levels did not significantly differ from pre-tumour endpoint levels for any diet group." (PMID 35908046, 2022). "However, systemic IGF-1 treatment did not alter tumor development in the mice injected with the naturally occurring densities of IGF-1R fibroblasts; this effect was dependent on the dose and the IGF-1R expression level." (PMID 35203722, 2022).
tumor (continued). "Besides, MIF-EGFR/TNFRSF14, IGF1/2-IGF1R/2 R, TNFSF12-TNFRSF12A (TWEAK-Fn14) interactions also mediated the crosstalk between TPF or SLF with EPCs, consistent with their function in facilitating tumor progression." (PMID 36198671, 2022). "Nineteen out of 28 patients reached biochemical remission, defined as an age-normalized serum IGF-1 value and a random GH of <1.0 ng/mL, and 20 out of 28 patients achieved radiological remission, defined as no recurrence or residual tumor on follow-up magnetic resonance imaging." (PMID 35019688, 2022). "Also based on the IGF-1 level and IGF-1R gene expression, the model could predict significantly the tumor grade (P=0.05) and tumor metastasis (P=0.02), respectively." (PMID 36713521, 2022). "The effect was independent of whether the tumor cells were exposed to IGF-1 in cell culture medium containing 0, 2 or 10% FBS." (PMID 35053528, 2022). "However, without estrogen signaling, it is attractive to speculate with the concept that tumor progression may be driven by other signaling factors such as fibroblast growth factor receptor-1 (FGFR-1), insulin growth factor 1 (IGF-1), or Ob-R." (PMID 34210055, 2021). "Acquired resistance to long-term CSF-1R inhibition was correlated with increased insulin-like growth factor (IGF-1) signaling between macrophages and tumor cells, leading to aberrant activation of phosphatidylinositol 3-kinase (PI3K) signaling, therefore promoting tumor cell survival and invasion." (PMID 34950148, 2021). "Furthermore, patients with a T2-hypointense tumor experienced a higher % IGF-1 reduction compared to the subjects with a non-hypointense lesion [65.8% (IQR 51.5-81.4) vs. 35.5% (IQR 23.4-62.9); p=0.021]." (PMID 34025586, 2021). "CAF with tumor-promoting functions secrete growth factors (HGF, IGF1, CTGF, PDGF, VEGF, LIF), cytokines (IL-1, IL-4, IL-6, IL-8, IL-10, TGF-β), and chemokines (CCL2, CCL5, CXCL5, CXCL9, CXCL10, CXCL12), WNT5α, and bone morphogenic protein 4 (BMP4), which promote tumor progression." (PMID 35008832, 2021). "Therefore, IGF1 and JUN play important roles in dysregulation of Ras protein signal transduction, which may be related to aberrant tumor immunity in DLBCL." (PMID 33107145, 2021). "Moreover, the relationship between IGF1/IGF1R expression and tumor prognoses, such as TMB, MSI, MMR, and DNMT, which can predict the efficacy of immunotherapy, remains unclear." (PMID 34804946, 2021). "However, the effect of the interaction between miR-186-3p and IGF1 on tumor growth in CC has not yet been established." (PMID 34551673, 2021). "Moreover, IGF1 has been described as a growth-regulatory MLL-ENL/Hoxa9/Meis1 target and as a direct C/EBPβ target gene involved in autocrine stimulation of transformed murine monocytes and in neoplasia." (PMID 33144337, 2021). "IGF-1 and IGF-2 are mainly produced in the liver, although some of them can also be synthesized from other tissue such as kidney, brain, or neoplastic tissue, regulating normal physiological processes or tumor growth by autocrine, paracrine, and endocrine manners." (PMID 33429867, 2021). "However, the relationship between IGF-1/IGF-1R overexpression and tumor immunity was still unclear." (PMID 34804946, 2021). "Insulin was found to stimulate insulin–IGF-1 signaling in tumor cells and result in an activation of the oncogenic Ras–MAPK and PI3K–Akt pathways (MAPK = mitogen-activated protein kinase, PI3K = phosphoinositide 3-kinase), which subsequently stimulate tumor cell growth." (PMID 33803268, 2021). "Knockdown of IGF-1 expression level via applying a CRISPR/Cas9 genome editing system could suppress the activation of AKT and Hedgehog signaling pathways, and thereby inhibiting cell proliferation, migration, and tumor aggressiveness in OSCC cells." (PMID 33768092, 2021). "IGF1R stimulates tumor metastasis and the secretion of invasion factors to the extracellular matrix, which is independent of the main signaling pathways related to IGF1." (PMID 34178997, 2021).
tumor (continued). "Importantly, when LIN activated the IGF-1/Akt/FoxO signaling pathway to inhibit skeletal muscle degradation, it showed no inhibition of the anti-tumour effect of DDP." (PMID 33390985, 2020). "Nevertheless, it is not clear whether IGF1 plays, by endocrine, paracrine, or autocrine mechanisms, a role in the etiology or only in the progression of neoplasms." (PMID 33182502, 2020). "For example, GH induces tumor growth without increasing IGF1." (PMID 33260481, 2020). "IGF-1/IGFBP-3 ratio has been shown to positively correlate with free IGF-1 and has been associated with a number of clinical outcomes, including functional status in nonagenarians, metabolic disease, and neoplastic diseases." (PMID 32492897, 2020). "Gender, IGF-1 index at diagnosis, and tumor size were not different between the 2 groups." (PMID 32311048, 2020). "However, the achievement of GH level ≤ 2.5 μg/L and/or the normalization of IGF-1 at 12 weeks of treatment, was not predictive of a significant reduction in tumor volume by the end of study." (PMID 31879842, 2020). "The relative expression of COL1A1, IGF1, COL5A1, CXCL12, and PTEN in tumor samples was significantly lower compared to those in adjacent normal samples (P < 0.05), while SPP1 expression was significantly higher in tumor samples compared to the adjacent normal samples (P < 0.05)." (PMID 32641130, 2020). "As a tumor is often described as being like a “chronic wound”, the hypoxic conditions and high concentration of cytokines and growth factors IL-1α, IL-1β, IL-6, FGF-2, IGF-1, TGF-β, VEGF-A, HIF-1α, EGF, TGF-α are a likely trigger for MSCs recruitment to tumor microenvironments." (PMID 31569731, 2019). "In addition, in patients with no biochemical significant response (<20% IGF-1 reduction) and without significant tumour shrinkage (<25% tumour volume reduction) during first-generation SRLs monotherapy, PEGV monotherapy is recommended." (PMID 31939490, 2019). "Although pegvisomant could normalize IGF-1 levels in 60–80% of patients, it cannot decrease GH levels or shrink tumor size because it does not have any direct effect on the tumors." (PMID 31191457, 2019). "Indeed, molecular studies have shown that IGFBP3 has biological functions that are independent of IGF1, such as involvement in tumor development and progression by mediating DNA damage responses, autophagy and apoptosis." (PMID 29947889, 2018). "Furthermore, none of the patients with tumours with score 1 exhibited an IGF‐1 reduction higher than 50% upon SSAs treatment." (PMID 29266696, 2018). "DLD-1 tumor spheres cultured with and without IGF1 were injected into NOD/SCID mice for evaluation." (PMID 30257507, 2018). "In the case of IGF1, an IGF1 mutant in which the Arg residues at positions 36 and 37 to Glu mutant, R36E/R37E was defective in inducing IGF1R signaling and suppressed cell proliferation induced by WT IGF1 in vitro and tumor growth in vivo (dominant-negative antagonistic action)." (PMID 28873464, 2017). "Additionally, as with PRL and PRLR, the base RNA levels of IGF1 were 3-fold lower than GH levels and the modulated-GH-action induced changes in IGF axis apparently had no observable variation on intracellular signaling or tumor phenotypes." (PMID 28223541, 2017). "The lack of castration effects in Dunning G tumor cells within the bone marrow cavity may be explained by the presence of other pro-survival and/or anti-apoptotic factors than IGF-1." (PMID 28447314, 2017).
tumor (continued). "The PI3K pathway may mediate the sensitivity of selected tumours to dietary restriction as tumours sensitive to dietary restriction were growth-responsive to insulin and IGF1 whereas tumours with constitutively active PI3K signalling were not." (PMID 28316059, 2017). "For instance, the involvement of insulin and IGF-1 in colorectal carcinogenesis could have increased free IGF-I with concomitant changes of environment mitogenesis and anti-apoptosis in the cells favouring tumour formation." (PMID 28778191, 2017). "Therefore, the increase in insulin and IGF1 levels, present in both obese and diabetic patients, may facilitate the EMT and tumor progression." (PMID 29383194, 2017). "Most patients with stable/controlled disease were characterized by a lack of signs and symptoms (6/9) and a single comorbidity (5/10), a GH nadir following an oral glucose tolerance test (OGTT) of ≤0.4 μg/L (2/2) or GH random/series ≤1 μg/L (7/8), normal IGF-1 levels (9/10), and no tumor (6/10)." (PMID 26377024, 2016). "In addition, in most cell lines IGF-1 could partially rescue the growth inhibitory effects of metformin, implying that simultaneously inhibiting IGF-1R might further improve the anti-tumor effect of metformin." (PMID 27488947, 2016). "EphA4‐KO tumor‐bearing mice without IGF1 administration showed a significant reduction in G‐CSF circulation level, which was enhanced by IGF1 treatment up to a level similar to that observed in WT tumor‐bearing mice." (PMID 26923183, 2016). "IGF1 administration could enhance the tumor growth almost to the WT level, but could not enhance the splenomegaly to the WT level." (PMID 26923183, 2016). "However, IGF1 administration did not significantly further increase the tumor weight of the control EphA4‐WT mice." (PMID 26923183, 2016). "The reason behind why IGF1‐stimulated tumor growth could not produce sufficient G‐CSF for splenic EMH to reach WT level is due to EphA4‐FGFR signaling, which regulates the MDSC proliferation." (PMID 26923183, 2016). "Since both insulin and IGF-1 have been reported to fuel some tumours, having more or less BAT may affect the overall systemic insulin sensitivity and thereby have an indirect influence of tumour progression." (PMID 26523094, 2015). "However, when the delayed treatment group is followed for 28 days, the tumor seems to acquire resistance to treatment, leading to tumor growth and increased expression of factors such as angiogenin, angiostatin, angiopoietin-1/2, EGF-R and IGF-1." (PMID 25549350, 2014). "Moreover, the increased IGF1 bioavailability in patients with HCC, probably as a consequence of autocrine secretion by the neoplasm, could be an important factor for tumour progression." (PMID 25225571, 2014). "Patients with higher expression of IGF-1 in adjacent liver than in tumor had significantly lower overall survival, suggesting that increased IGF-1 synthesis by neighboring hepatocytes may lead to aggressive tumor biology." (PMID 25052889, 2014). "In the multivariate analysis, IGF-1 levels lower than 56 ng/mLremained a significant risk factor for poorer OS (HR, 1.889; 95% CI, 1.128–3.163; P = 0.02), together with BCLC stage, larger tumor size, and mRECIST non-responders." (PMID 24595361, 2014). "In addition, it appears that the tumour suppressor function of DACH1 can be moderated by the tissue microenvironment including the presence of growth factors, evidenced by tumorigenesis seen in cell lines grown in vitro in the presence of IGF-1." (PMID 24392136, 2014).
tumor (continued). "While there was no single pathway significantly up-regulated in all three tumor models, there were some pathways up-regulated in two models, such as proteasome in the xmrk and Myc models, and IGF1 pathway, mTOR pathway, tRNA biosynthesis and focal adhesion in the xmrk and kras models." (PMID 24633177, 2014). "At 4 weeks on HFD, the levels of OPG and IGF-1 were significantly elevated (1.3-fold, P = 0.04 and 1.3-fold, P = 0.005, respectively); this increase was transient and not seen at later time points, or in tumor-bearing mice." (PMID 24156623, 2013). "However, a recent study showed that transfection of TRβ1 into human SK-hep1 cells reduced HCC xenograft tumor growth in nude mice, promoted partial mesenchymal-to-epithelial transition, attenuated tumor cell invasiveness, and blocked tumor cell responses to growth factors EGF, IGF-1, and TGF-β." (PMID 23924944, 2013). "While some authors found that the decline of GH and/or IGF-1 concentration predicted tumour shrinkage in therapy naive patients, other could not demonstrate a correlation between biochemical efficacy and tumour shrinkage." (PMID 22550484, 2012). "In our study, the IGF-1 and IGF-2 mRNA levels are much higher in tumor cells and tumor-adjacent cells than those in control tissues, suggesting that IGF-1 and IGF-2 may be a critical mediator for transforming from normal cell into tumor cells." (PMID 22720981, 2012). "Here we show that IGF-1 activates matrix metalloproteinase that have the potential to cleave the ECM and may release potent bioactive molecules leading to possible growth, proliferation and metastasis of a primary tumor." (PMID 21535875, 2011). "The positive correlations observed between serum Ang-2 and serum C-peptide (a stable marker of circulating insulin levels), and between VEGF-A and IGF-1 in males, may implicate insulin and IGF-1 in promoting a systemic pro-angiogenic environment, and potentially increasing tumour angiogenesis." (PMID 21081932, 2011). "Although the VEGF level is correlated to tumor resectability, the bFGF and IGF-1 were not." (PMID 24212642, 2011). "The ORs varied according to oestrogen-receptor status; the OR for a linear trend in IGF1 was significant among oestrogen-receptor positive cases (OR 1·38, 95% CI 1·14–1·68), but not for oestrogen-receptor negative tumours (OR 0·80, 0·57–1·13) and the test for heterogeneity was significant (p=0·007)." (PMID 20472501, 2010). "Furthermore, because the efficacy of pegvisomant is not dependent on tumor somatostatin receptor expression, pegvisomant effectively inhibits IGF-1 secretion in patients who are non- or partial responders to somatostatin analogues." (PMID 20478050, 2010). "Thus, surprisingly, a positive effect of IGF-1 alone on invasive capacity in this tumour type had not been documented until now." (PMID 18598360, 2008). "Accordingly it is implied, but not proven, that increased levels of IGF-1 in the aged prostate could promote endothelial cell function thereby resulting in similar levels of vascularisation, and primary tumour growth, in young and old hosts." (PMID 18182993, 2008). "Additionally, growth factors such as insulin-like growth factor 1 (IGF1), basic fibroblast growth factor (bFGF), vascular endothelial growth factor (VEGF), platelet-derived growth factor (PDGF), and transforming growth factor-β (TGF-β) can also recruit MSCs into the tumor environment." (PMID 39971901, 2025). "Although our study may have had insufficient power to examine these associations, as these measurements were done only on a subset of mice, our results suggest that consuming a LoGI diet may not inhibit the insulin/IGF-1 pathway strongly enough to impact tumor growth." (PMID 38082056, 2024). "Also, the insulin/IGF-1 pathway and its consequences are not a consensus for all tumors in dogs; thus, it could play a role or not depending on the type of tumor." (PMID 40046187, 2024).